Y_RNA (Y RNA )
Gene: Miscellaneous RNA gene on chromosome 19 (56,316,524 to 56,316,636, reverse strand). Ensembl gene ENSG00000200646.
Homologues: Orthologues: chimpanzee Y_RNA (99% identical). Paralogues in human: RNY1 (86% identical), Y_RNA (85% identical), Y_RNA (83% identical), RNY1P11 (81% identical), Y_RNA (81% identical), RNY1P10 (80% identical), RNY1P8 (80% identical), Y_RNA (80% identical), Y_RNA (79% identical), RNY1P5 (78% identical), Y_RNA (78% identical), Y_RNA (77% identical), and 93 more.